CXCL1 (C-X-C motif chemokine ligand 1)
Diseases named in the same sentence as CXCL1 in open-access papers (continued):
Sharing a sentence is not in itself a finding about the gene and the disease.
systemic sclerosis (2 papers, 2021 to 2022). A chronic disorder, possibly autoimmune, marked by excessive production of collagen which results in hardening and thickening of body tissues. "It has been shown that serum CXCL1 concentrations are specific to systemic sclerosis (SSc) and correlated with the involvement of internal organs, especially pulmonary damage." (PMID 34961474, 2021).
thymoma (2 papers, 2015 to 2023). A neoplasm arising from the epithelial cells of the thymus. "In MG patients with versus without thymoma, 58 lncRNAs had 271 ‘cis’ genes upstream or downstream of their chromosomal position: lncRNA oebiotech_22652 had the highest number of ‘cis’ genes, whereas lncRNA oebiotech_12244 had 6 ‘cis’ genes(PPBP, CXCL1, CXCL5, PF4V1, PF4, and C14orf45)." (PMID 25889429, 2015).
tick-borne encephalitis (2 papers, 2018 to 2022). Tick-borne encephalitis is caused by an arbovirus of the Flaviviridae family (tick-borne encephalitis virus, TBEV), transmitted principally by the bite of the Ixodes ricinus tick. "Concentrations of IL-17A, IL-17F, IL-22, CXCL1, and CXCL2 in serum (S) samples obtained from tick-borne encephalitis patients on admission to hospital are shown horizontal axes and in cerebrospinal fluid (CSF) samples obtained simultaneously on vertical axes (expressed in pg/ml)." (PMID 29678185, 2018).
urinary tract infection (2 papers, 2018 to 2025). "In line with our findings, absence of CXCL1 upregulation has also been recently reported in SP-A/SP-D double-deficient mice subjected to urinary tract infection." (PMID 30619359, 2018).
urothelial carcinoma (2 papers, 2018 to 2023). A malignant neoplasm derived from the transitional epithelium of the urinary tract (urinary bladder, ureter, urethra, or renal pelvis). "Immunohistochemical evaluation of tumours from urothelial carcinoma patients supported the correlation between high CXCL1 expression and reduced survival." (PMID 36810912, 2023). "CXCL1 and CXCL3 related to the nuclear factor kappa B and nuclear factor (erythroid-derived 2)-like 2 signaling pathways were measured in human urothelial carcinoma cell lines." (PMID 29854840, 2018). "Next, we investigated the clinical relevance of CXCL1 by collecting tumour tissues from 40 recurrent urothelial carcinoma patients who received TURBT but did not undergo radiation." (PMID 36810912, 2023).
urticaria (2 papers, 2022 to 2025). A vascular reaction of the skin characterized by erythema and wheal formation due to localized increase of vascular permeability. "Supporting this, mast cells have been demonstrated to recruit neutrophils, for example, via CXCL-1 during tissue inflammation, or IL-1β in urticaria." (PMID 35558068, 2022).
uterine cancer (2 papers, 2019 to 2023). Primary or metastatic malignant neoplasm involving the uterine corpus and/or the cervix. "A study in a mouse model of uterine cancer found that neutrophils largely resided within hypoxic foci, and the culture of uterine cancer cell lines in hypoxia led to the expression of potent neutrophil chemo-attractants; CXCL1, CXCL2, and CXCL5." (PMID 31461847, 2019). "Notably, analysis of TCGA Pan-Cancer Atlas showed a consistent positive correlation between SERPINB3 and CXCL1, CXCL8, S100A8, and S100A9 across multiple tumor types including bladder, breast, head and neck, lung, prostate, and uterine cancers." (PMID 37279067, 2023).
viral pneumonia (2 papers, 2022 to 2023). Inflammation of the lung parenchyma that is caused by a viral infection. "In cerebral and pulmonary tissues, the P9 virus replication induced the production of G-CSF, IFN-γ, IL-6, CXCL1, MCP-1, MIP-1α, RANTES, IP-10, MIP-1β, and TNF-α, as well as pathological alterations including reduction of neuronal cells and typical symptoms of viral pneumonia." (PMID 35755996, 2022).
vitamin D (2 papers, 2013 to 2014). "Upon A. fumigatus exposure, vitamin D deficiency led to enhanced and sustained expression of TNF-α, IL-1β, IL-6, CXCL1 and CCL3 both in vivo and in vitro." (PMID 24926881, 2014). "Increased expression of CCL19 mRNA was observed in the CD11c+ cells from male vitamin D-deficient mice, when compared to their vitamin D-replete counterparts, while vitamin D deficiency down-regulated the expression of mRNAs of CCL11, CCL19, CCL20 and CXCL1 in CD11c+ cells from female mice." (PMID 23826346, 2013).
acute GVHD (1 paper, 2026). "In contrast, elevated IL-6, IL-17A, PAI-1, IL-10, CX3CL1, CXCL1, and CCL4 levels were prognostic for quiescent cGVHD compared with patients with resolved acute GVHD only." (PMID 41798937, 2026).
Acute hepatic failure (1 paper, 2015). Hepatic failure refers to the inability of the liver to perform its normal synthetic and metabolic functions, which can result in coagulopathy and alteration in the mental status of a previously healthy individual. "Early acute hepatic failure has been shown to upregulate central cyto/chemokines, including CXCL1, which mediate neurotoxic effects independently of microglial activation." (PMID 25994490, 2015).
Acute hepatitis (1 paper, 2013). Acute hepatic injury resulting from inflammation typically accompanied by increased serum alanine transaminase activity. "The increased CXCL1 during MHV3 induced acute hepatitis may lead to chemotaxis/infiltration of neutrophils as an early response to liver infection and development of inflammatory microenvironment." (PMID 24058536, 2013).
acute liver failure (1 paper, 2019). Rapid deterioration of liver function causing encephalopathy and coagulopathy. "CCL11 (Eotaxin) was selectively increased in biliary atresia patients, while IL-3, IL-6, CXCL8 (IL-8), IL-9, IL-16, MIF, CCL4 (MIP-1 β), and CXCL1 (GRO-α), were increased in both biliary atresia and acute liver failure." (PMID 30740106, 2019).
acute pyelonephritis (1 paper, 2021). "In this respect, increased transcripts of CXCL1 gene have been documented also in renal biopsies of patients with acute pyelonephritis." (PMID 33776571, 2021).
adenovirus infection (1 paper, 2010). "CXCL1 and CCL2 have been shown to be expressed in adenovirus infection and are paradigm chemokines responsible for neutrophil and monocyte chemotaxis, respectively." (PMID 20419141, 2010).
age (1 paper, 2025). A temporal measurement of the time period elapsed since an identifiable point in the life cycle of an organism. "Thus, CXCL1 is a significant SASP component mechanistically linked to senescence: it reinforces senescence via autocrine signaling, and its presence in the secretome can modulate immune surveillance and tissue outcomes in age-related pathologies." (PMID 40791849, 2025).
age-related macular degeneration (1 paper, 2015). Age-related loss of vision in the central portion of the retina (macula), secondary to retinal degeneration. "In the retina, upregulation of α and β chemokines, such as Ccl2, Cxcl1, and Cxcl10 have been detected by gene expression analyses in both wet and dry forms of age-related macular degeneration (AMD)." (PMID 25595590, 2015).
AIDS (1 paper, 2025). A syndrome resulting from the acquired deficiency of cellular immunity caused by the human immunodeficiency virus (HIV). "Integrative multi-omics further highlighted seven neutrophil-associated KGs, especially CXCL1, which exhibited robust diagnostic performance and consistent dysregulation across AIDs." (PMID 41425547, 2025). "CXCL1 has been identified as a key chemokine in several inflammatory disorders, including AIDs, and targeting this pathway could represent a novel therapeutic strategy for RM management." (PMID 41425547, 2025).
AIDS dementia complex (1 paper, 2021). A neurologic condition associated with the ACQUIRED IMMUNODEFICIENCY SYNDROME and characterized by impaired concentration and memory, slowness of hand movements, ATAXIA, incontinence, apathy, and gait difficulties associated with HIV-1 viral infection of the central nervous system. "Furthermore, it is reported that upregulated expression of CXCL1 fractalkine is observed in patients suffering from AIDS dementia complex (ADC) as well as in in vitro cultures of HIV-infected astrocytes and macrophages." (PMID 34483726, 2021).
allergic rhinitis (1 paper, 2019). Inflammation of the nasal mucous membranes caused by an IgE-mediated response to external allergens. "Increased level of CXCL1 has been reported in a mouse model of allergic rhinitis." (PMID 31024564, 2019).
arbovirus infection (1 paper, 2025). A viral infection that is transmitted by an arthropod. "This included a crucial set of genes that have been implicated in increased susceptibility to arbovirus infection, including neutrophil-attracting chemokines (CXCL1, CXCL3, CXCL8)." (PMID 41150413, 2025).
arteritis (1 paper, 2024). An inflammatory process affecting an artery. "Il17ra-deficiency mice developed less LCWE-induced arteritis with fewer neutrophil infiltration, absent aortic IL-17RA augmentation, and less early Inos and Cxcl1 upregulations." (PMID 38451335, 2024).
autoimmune glomerulonephritis (1 paper, 2024). An autoimmune form of glomerulonephritis (disease). "Promotion of autoimmune glomerulonephritis by IL-17 is mediated, in part, by m6A modification of RNA and functional IGF2BP2 (IMP2) binding of selected transcripts: Cebpd, Ccl7, Mt2, Il-6, and Cxcl1." (PMID 39338937, 2024).
Barrett esophagus (1 paper, 2023). Esophageal lesion lined with columnar metaplastic epithelium which is flat or villiform. "An elevated expression of CXCL1 has been observed in Barrett’s esophagus and esophageal adenocarcinoma compared to healthy tissue." (PMID 37408240, 2023). "The increase in CXCL1 expression in Barrett’s esophagus and esophageal adenocarcinoma is also due to the frequent amplification of the CXCL1 gene as well as hypomethylation of its promoter." (PMID 37408240, 2023).
benign ovarian tumors (1 paper, 2020). "Using LASSO regression, a multiplex model including 6 biomarkers (HE4, CA125, ITGAV, CXCL1, CEACAM1, IL-10RB) and age had the highest diagnostic accuracy for discrimination between benign ovarian tumors and EOC including borderline tumors." (PMID 33075095, 2020).
biliary atresia (1 paper, 2019). A rare, biliary tract disease characterized by progressive obliterative cholangiopathy of the intra- and extrahepatic bile ducts, occurring in the embryonic/ perinatal period, leading to severe and persistent neonatal jaundice and acholic stool. "The clinical relevance of the elevation of CXCL1 (GRO-α) in biliary atresia remains unclear." (PMID 30740106, 2019). "In children with biliary atresia, serum levels of CCL11 (Eotaxin), IL-16, and GRO-α (CXCL1), as well as numbers of B lymphocytes, were higher than in children with ALF or liver tumors." (PMID 30740106, 2019).
bladder disorders (1 paper, 2017). "Chemokines are known contributors to symptoms of bladder disorders, and Perters found remarkably reduced levels of chemokines CXCL-1, CXCL-10, and CCL-2 in patients who had received sacral neuromodulation therapy for BPS/IC." (PMID 28106785, 2017).
bladder urothelial carcinoma (1 paper, 2025). "Research indicates that CXCL1 expression in bladder urothelial carcinoma (UCB) exhibits significant clinical heterogeneity." (PMID 41445742, 2025).
bone metastasis (1 paper, 2023). Transfer of a neoplasm from its primary site to bones. "Cells of the PC-3 line (isolated from bone metastasis) mainly produce CXCL8/IL-8, while cells of the DU 145 line (isolated from brain metastasis) mainly produce CXCL1." (PMID 37108425, 2023).
Brain atrophy (1 paper, 2021). Partial or complete wasting (loss) of brain tissue that was once present. "The CHI3L1 (chitinase-3-like protein 1) level in the CSF was strongly correlated with brain atrophy, and the CSF levels of CXCL1, MMP-9, CCL22, CXCL13, and CXCL10 were correlated with the development of new lesions in T2 MRI." (PMID 34602928, 2021).
breast ductal carcinomas (1 paper, 2014). "In these studies, we can only conclude that CXCL1 is expressed in the stroma of breast ductal carcinomas of multiple histologic subtypes." (PMID 25344051, 2014).
bronchiolitis (1 paper, 2022). Inflammation of the bronchioles characterized by swelling of the bronchioles and mucus accumulation. "Additionally, in mock-primed mice, the degree of neutrophilic infiltration and the increased expression of chemokines and neutrophil activators, especially CXCL1 and CXCL2, into the lungs following PVM inoculation has been positively correlated with the severity of hRSV-induced bronchiolitis." (PMID 35062301, 2022).
bubonic plague (1 paper, 2012). A plague in which the bacteria have infected the lymphatic system. "A recent study of the systemic phase of bubonic plague due to fully virulent Y. pestis CO92 showed high levels of the PMN maturation factor G-CSF, chemokines CXCL1 and CCL2, as well as cytokines IL-6 and Il-1α in plasma." (PMID 23248776, 2012).
Candida systemic infection (1 paper, 2024). "IFN-I signaling controls the recruitment of inflammatory myeloid cells, including Ly6Chi monocytes and neutrophils, to infected mouse kidneys by driving the expression of the chemokines CCL2 and CXCL1, which aggravates renal immunopathology during Candida systemic infection." (PMID 38166150, 2024).
Candidemia (1 paper, 2025). A form of invasive candidiasis where species of CANDIDA are present in the blood. "The proteomic profile in candidemia included eight of the most significantly upregulated DEPs: CXCL11, LAP-TGF beta-1, CD40, CXCL1, CXCL6, IL18, CXCL10, and uPA." (PMID 41229429, 2025). "The highest upregulated expressions in isolated candidemia included CXCL6, LAP-TGF beta-1, CXCL1, CXCL11, and CD5, while in candidemia with bacterial co-infection, CXCL11, CD40, uPA, CXCL1, CXCL10, and IL-18 were the most abundantly upregulated." (PMID 41229429, 2025).
cerebral aneurysm (1 paper, 2025). "CXCL1 has been reported to play a crucial role in M1 macrophage polarization during cerebral aneurysm development." (PMID 39890803, 2025).
cerebral infarction (1 paper, 2021). An ischemic condition of the brain, producing a persistent focal neurological deficit in the area of distribution of the cerebral arteries. "Brain tissues of MCAO model rats showed significantly increased cerebral infarction areas, cerebral water, neuronal apoptosis, and activated CXCL1/CXCR2/NF-κB signaling, but these effects were alleviated by intraventricular injection of miR-532-5p agomir." (PMID 33867350, 2021).
chondrosarcoma (1 paper, 2012). A malignant cartilaginous matrix-producing mesenchymal neoplasm arising from the bone and soft tissue. "All three are in the “multifunctional” signature of dedifferentiated chondrosarcoma lung metastases—MMP1 and CXCL1 were significantly differentially expressed in 4 out of 5 metastases; TNC was differentially expressed in all 5 metastases and it is also a component of the “biased” signature)." (PMID 22448124, 2012).
chronic bronchitis (1 paper, 2017). A type of chronic obstructive pulmonary disease characterized by chronic inflammation in the bronchial tree that results in edema, mucus production, obstruction, and reduced airflow to and from the lung alveoli. "In this context, our results revealed that the effectiveness of the model to induce chronic bronchitis is mainly characterized by increased number of neutrophils and lymphocytes in BAL, followed by increased levels of proinflammatory cytokines (IL-1β, IL-6, CXCL1, IL-17, and TNF-α)." (PMID 29326759, 2017).
chronic endometritis (1 paper, 2022). A non-granulomatous or granulomatous chronic inflammation of the endometrium. "Studies have found that the chemokines CXCL1 and CXCL13 are abnormally expressed in female infertility patients with chronic endometritis." (PMID 36003498, 2022).
chronic granulomatous disease (1 paper, 2007). Chronic granulomatous disease (CGD) is a rare primary immunodeficiency, mainly affecting phagocytes, which is characterized by an increased susceptibility to severe and recurrent bacterial and fungal infections, along with the development of granulomas. "Microarray analysis of blood PMN from patients with X-linked chronic granulomatous disease revealed increased mRNA levels for only two chemokines, namely CXCL8 and CXCL1." (PMID 17875202, 2007).
chronic GVHD (1 paper, 2021). "Serum measures of CXCL1 and CXCL10 were induced in acute and chronic GVHD patients in compare to these without GVHD." (PMID 34711015, 2021).
chronic hepatitis (1 paper, 2023). An active inflammatory process affecting the liver for more than six months. "How elevated CXCL1 expression levels affect chronic hepatitis function in HCC has been poorly delineated." (PMID 37037815, 2023).
chronic liver failure (1 paper, 2024). Liver failure that develops slowly and gradually for some time, possibly for years, often as the result of cirrhosis, or malnutrition. "CXCL1 plays a pivotal role in neutrophil mobilization in acute and chronic liver failure, and the suppression of CXCL1 attenuates neutrophil infiltration and decreases apoptosis of hepatocytes by reducing ROS levels." (PMID 39000295, 2024).
chronic lung infection (1 paper, 2020). "Th17 lineage cytokines (IL-17A, IL-17F, and IL-22) and chemokines (CXCL1, CXCL2, CXCL5, and CXCL8) are known to control chronic lung infection caused by mycobacteria." (PMID 33520738, 2020).
chronic otitis media (1 paper, 2019). Chronic form of otitis media (disease). "Specifically, CXCL1 mRNA was upregulated in the inner ear tissue of mice with chronic otitis media, based on qRT-PCR analysis." (PMID 31632328, 2019).
congestive heart failure (1 paper, 2016). Failure of the heart to pump a sufficient amount of blood to meet the needs of the body tissues, resulting in tissue congestion and edema. "Damås and colleagues showed that circulating levels of CXCL8, CXCL1 (GRO-α), and CXCL5 (ENA-78) gradually increased in patients with congestive heart failure (CHF) in parallel with an increase in NYHA functional class." (PMID 27242392, 2016).
corneal infection (1 paper, 2017). A viral or bacterial infectious process affecting the cornea. "CXCL1 mediates effective clearance and resolution of corneal infections, and is critical for pseudomonas keratitis, in particular." (PMID 28796783, 2017).
coronary atherosclerosis (1 paper, 2024). Atherosclerosis of the coronary vasculature. "ENPP2 has been documented to promote coronary atherosclerosis by mediating LDL production through the generation of LPA 20:4, 16:0, and 18:1 and by inducing CXCL1 expression." (PMID 39731014, 2024).
Cough (1 paper, 2017). A sudden, audible expulsion of air from the lungs through a partially closed glottis, preceded by inhalation. "The poly(I:C)-induced release of inflammatory mediators, including CXCL8, interleukin (IL)-6 and CXCL1, from ASMCs from cough patients was significantly impaired compared with healthy non-cough subjects." (PMID 28842514, 2017).
cowpox (1 paper, 2013). A mild, eruptive skin disease of milk cows caused by cowpox virus, with lesions occurring principally on the udder and teats. "The role of IL-6 induction in cowpox pathogenesis remains still unclear but a recent article evidenced that IL-6, IL-8 and CXCL1, produced upon in vitro CPXV-BR infection, could be responsible for chemotaxis of monocytes in vitro." (PMID 23457480, 2013).
Crush Syndrome (1 paper, 2022). Severe systemic manifestation of trauma and ischemia involving soft tissues, principally skeletal muscle, due to prolonged severe crushing. "The expression levels of inflammatory cytokines and chemokines (e.g., TNFα, IL-6, CXCL1, CXCL2, CXCR2, CCL2) in crush syndrome were significantly suppressed in TPEN-treated group." (PMID 36114355, 2022).
Cryptogenic fibrosing alveolitis (1 paper, 2024). "Cryptogenic fibrosing alveolitis (CFA) is characterized by increased pulmonary recruitment of peripheral blood neutrophils, and plasma levels of CXCL1 were elevated in patients with CFA and may contribute to neutrophilic cryptogenic fibrosing alveolitis." (PMID 39768150, 2024).